AFP (alpha fetoprotein)
Diseases named in the same sentence as AFP in open-access papers (continued):
Sharing a sentence is not in itself a finding about the gene and the disease.
tumor (continued). "Furthermore, serum biomarkers such as β-HCG and AFP are also nonspecific for this kind of tumor." (PMID 29804543, 2018). "Subcutaneous injection of Dt81Hepa1-6 cells in C57BL/6 mouse resulted in tumors developing macroscopically in the liver as confirmed by AFP expression (8.5±3.9 fold changes; P<0.05) but no tumor could be observed either in the lungs, subcutaneous site of injection or spleens in these mice." (PMID 28152020, 2017). "In addition to these tumor characteristics, biomarkers for preserved liver function and the liver damage status of the HCC patients, such as the Child-Pugh stage; the α-fetoprotein (AFP), bilirubin, and albumin levels; and ECOG status are also associated with the prognosis of HCC patients." (PMID 28434945, 2017). "Interestingly, the tumor cells were found to express Bmi1, AFP and albumin, but not CK19." (PMID 26926789, 2016). "Although the ability to correlate tumor size with rat alpha-fetoprotein has been described, to date, we have not found a commercial test for alpha-fetoprotein that demonstrates cross-reactivity with rat alpha-fetoprotein to allow serum monitoring (data not shown)." (PMID 26180705, 2015). "However, the sensitivity and specificity of AFP are not sufficient for clinical requirement and ultrasound examination could not find tumor with <1 cm diameter." (PMID 26583119, 2015). "In addition, of patients who showed a discordant tumor marker response (A↓P↑ or A↑P↓), those of the A↑P↓ group who were AFP nonresponders had better progression-free and overall survival than did A↓P↑ patients (10.1 versus 5.1 months, P = 0.038; 22.4 versus 7.3 months, P = 0.038, resp)." (PMID 24455683, 2013). "Furthermore, Cox univariate analysis also revealed that the clinicopathological variables could provide significant predictive values for recurrence including preoperative AFP level, tumor size and CIMP status (data not shown)." (PMID 20678188, 2010). "However, neither AFP nor subunits of hCG are able to differentiate between NETs and other tumours." (PMID 18577995, 2008). "Although tumor markers (CA19-9 and alpha-fetoprotein) were transiently elevated, the absence of malignant masses on imaging and the subsequent normalization of CA19-9 levels following treatment led to the exclusion of malignancy-associated jaundice." (PMID 41578473, 2026). "No tumor was found in the ovaries, and the investigated tumor markers (CEA, hCG, alpha-fetoprotein, LDH, and Ca-125) were in the reference ranges." (PMID 41515619, 2026). "AFP (352,030 ng/mL) and lactate dehydrogenase (LDH) (2232) levels were significantly elevated, while other tumor markers, including CA 19‐9 and CEA, showed no abnormalities." (PMID 41523302, 2026). "We also conducted a correlation analysis between EIF5A2 and clinicopathological characteristics and showed that EIF5A2 expression was correlated with tumor size, differentiation degree, and TNM stage, but not with gender, age, AFP level, and vascular invasion." (PMID 40964657, 2025). "When specific CTAs were detected in AFP-negative HCC, mRNAs were proposed as tumor markers to identify circulating HCC cells as an adjuvant diagnostic tool, as well as indicators of prognosis and recurrence." (PMID 41614820, 2025). "This score is composed of 29.5 points for tumor number, 27 points for tumor differentiation, and 41 points for postoperative PIVKA-II, with no points assigned for preoperative SII or postoperative AFP." (PMID 40808940, 2025). "Tumoral markers were negative [CEA, CA-125, CA19-9, CA15-3, B inhibin, and alpha-fetoprotein (AFP)]." (PMID 40370432, 2025). "The risk of short OS in the ΔsADC positive group was lower than that in the ΔsADC non-positive group, except for the subgroups of age ≥ 60, female, PD-L1 usage, tumor number > 3, without PVTT, BCLC-B stage, ECOG PS ≥ 1, no HBV infection, and AFP < 400 ng/mL." (PMID 41137952, 2025).
tumor (continued). "Immunohistochemical staining showed that the tumor tissue was positive for CgA, Syn, S - 100, CD10, and CD34, but negative for AFP, cytokeratin 19 (CK19), CK7, GS, GPC3, HSP70, with a Ki-67 labeling index of 2%." (PMID 40978045, 2025). "The tumor was negative for epithelial markers (Pan CK, EMA, CK7, CK20, CK19, CK8, CEA), hepatocellular markers (AFP, HepPar-1), and other markers (CD34, Fli-1, ERG, CD99, S-100, Sox10, HMB45)." (PMID 41332073, 2025). "The variables with p < 0.05 in univariate Cox regression analysis included BCLC stage, presence or absence of distant metastasis, maximum tumor diameter, TACE times, and AFP level." (PMID 40678062, 2025). "Results of tumor markers were obtained, demonstrating negative CEA, CA 19-9, and AFP levels and elevated chromogranin A and 5-HIAA levels." (PMID 40718311, 2025). "The remaining 8 indicators, tumor hemorrhage and necrosis, maternal history, surgical approach, tumor papilla, CA199, AFP, CEA, and pre-ROMA index, were not statistically significant." (PMID 39911631, 2025). "Immunohistochemically, the tumor was positive for SALL4 and negative for CD30, AFP, OCT3/4, PLAP, D2‐40, and hCG." (PMID 41185737, 2025). "However, elevated tumor markers (CEA, CA199, AFP) were significantly associated with higher mortality risk (CEA: P for overall = 0.001, P for non-linearity = 0.014; CA199: P for overall = 0.018, P for non-linearity = 0.034; AFP: P for overall = 0.011, P for non-linearity = 0.008)." (PMID 41245411, 2025). "Therefore, the PS score, tumor number, maximal tumor size, ES classification, microvascular invasion, AST and GGT were the significant independent risk factors of OS, while the combination with TACE/RFA, satellite nodule, TNM staging, AFP and PAB were the risk factors without significance." (PMID 41180318, 2025). "Serum was negative for the tumor biomarkers β-HCG, alpha-fetoprotein, carcinoembryonic antigen (CEA), and CA-125." (PMID 40313596, 2025). "Although alpha-fetoprotein (AFP) is a well-known biomarker for HCC, poor sensitivity and specificity resulting from non-secretion by a considerable fraction of HCC tumor cells reduce its therapeutic utility." (PMID 39335728, 2024). "The levels of vitamin B12, folate, antinuclear antibody (ANA), Scl-70 antibody, SSA 52 (Ro) (ENA) antibody, SSA 60 (Ro) (ENA) antibody, SSB (La) (ENA) antibody, alpha-fetoprotein (AFP), tumor markers CA 125 and CA 19-9 were also within normal limits." (PMID 39135820, 2024). "Five weeks after injection, Dhx15+/− mice exhibited similar tumor size and low, nonsignificant expression levels of the HCC marker alpha-fetoprotein (AFP) compared to wild-type mice." (PMID 38612527, 2024). "When we studied the relationship between miR-497 and a variety of pathological parameters in patients with HCC, we found that the low expression of miR-497 was not significantly correlated with TNM stage, sex, age, AFP level, HBV infection, and tumor size." (PMID 38529202, 2024). "No statistical differences were observed in sex, age, AFP level, MVI, and tumor size between these two groups." (PMID 38415224, 2024). "Tumoural PD-L1 expression was independent of key clinicopathologic features of HCC including BCLC stage (p = 1.0), CTP class (p = 0.403), AFP >400 ng/ml (p = 0.595), and presence of portal vein thrombosis (p = 1.0)." (PMID 37274775, 2023). "Although AFP is of great importance in damage repair during CVH, there is still a lack of documentation on how to use it other than as a tumor exclusion indicator to evaluate the capability of hepatocyte regeneration." (PMID 36761898, 2023). "Patients with a limited tumor burden, defined as <4 tumors and maximal tumor size ≤10 cm, compensated liver function, absence of HCC rupture, and AFP concentration <400 ng/mL, were found to benefit most from TACE." (PMID 37346065, 2023). "Twelve months after chemotherapy, at outpatient follow-up, MRI demonstrated no tumor relapse, accompanied by β-HCG and AFP levels within the normal range." (PMID 38066820, 2023).
tumor (continued). "In MR enhanced and diffusion imaging, tumour without capsule, persistent enhancement and DWI targetoid findings, combined with AFP > 20 μg/L and HBV infection-positive laboratory results, can help to diagnose DPHCC and differentiate it from NCPHCC and ICC." (PMID 37578576, 2023). "The level of serum alpha-fetoprotein (AFP) had risen to 1210 ng/mL, significantly higher than normal (0–9 ng/mL), while other tumor markers were within the normal range." (PMID 37344881, 2023). "The tumor marker [lactate dehydrogenase (LDH), alpha-fetoprotein (AFP), and beta-human chorionic gonadotropin (β-HCG)] found no abnormality." (PMID 36923765, 2023). "The conventional risk factors for recurrence include nonanatomical resection, tumor size, microvascular invasion (MVI), serum alpha-fetoprotein level (AFP) and multiple tumors." (PMID 36969018, 2023). "Excluding this grouping and comparing the existence of histological HCC and total tumor diameter with M2BP index or tumor markers, there was a significant difference only in AFP values with and without HCC." (PMID 37910585, 2023). "Among the tumor markers before and after RFA, neither AFP nor DCP levels showed significant difference in recurrence-free survival." (PMID 36832184, 2023). "Accordingly, tumor staging and Lugano classification was less favorable for the AFP/HCG + than AFP/HCG- cancers in both hormonal subsets." (PMID 37669975, 2023). "The neoplasm was positive for CK7, CK19, and synaptophysin; weakly positive for pCEA and chromogranin; and negative for nuclear β-catenin, Hep-Par1, glypican-3, alpha-fetoprotein, and glutamine synthetase." (PMID 36782322, 2023). "In all of the mismatch cases either in HCG or AFP, tumor was located at pineal gland with (n = 2) or without (n = 8) neurohypophysis (one case was an overlap in HCG and AFP)." (PMID 36995447, 2023). "In terms of immunophenotype, the tumor cells are positive for cytokeratin (CK) and chorionic gonadotropin (hCG) expression and negative for CEA and alpha-fetoprotein, with the Ki-67-positive index is >80%." (PMID 37724114, 2023). "Testicular tumor markers, including lactate dehydrogenase (LDH), alpha-fetoprotein (AFP), and Beta-human chorionic gonadotropin (ß-HCG) did not reveal any pathological finding." (PMID 37565109, 2023). "Treatment with JPHYD yielded significant OS advantages for females, patients ≥ 60 years, and patients with BCLC A, single tumor, maximum tumor diameter ≤ 8 cm, without MVI, AFP < 400, HBV DNA ≤ 1,000, ICG ≤ 10%, or Child-Pugh A grade disease." (PMID 37818186, 2023). "Multiple risk factors associated with ER have been identified, such as microvascular invasion (MVI), high preoperative alpha fetoprotein (AFP) level, chronic active hepatitis, the absence of a tumor capsule, and large tumor size." (PMID 35715787, 2022). "The median serum levels of LC-SPIK, AFP, and PIVKA-II were significantly higher in patients with HCC compared to those without tumor (LC-SPIK: 24.3, 17.6–39.8 ng/mL vs. 11.7, 8.7–18.2 ng/mL; p < 0.001." (PMID 36005169, 2022). "The levels of tumor markers, such as CEA, CA19-9, CA125, and alpha fetoprotein, were not significantly different between patients with GC in the lesser curvature and those with GC in the greater curvature." (PMID 35984169, 2022). "Other non-mucin glycoproteins, i.e., alpha-fetoprotein (AFP), carcinoembryonic antigen (CEA), and squamous cell carcinoma antigen (SCC-Ag), are well-documented tumor markers in different kinds of cancer." (PMID 36553184, 2022). "The tumor size, vascular invasion, AST, ALT, and albumin levels, but not AFP levels, were significantly different between both groups (p < 0.001)." (PMID 35455635, 2022). "Serum levels of tumor markers (carcinoembryonic antigen (CEA), CA19-9, alpha-fetoprotein (AFP), and des-gamma-carboxy prothrombin were all within normal limits and she was negative for hepatic viral markers (HBsAg and anti-HCV)." (PMID 36107353, 2022).
tumor (continued). "Among all patients, nine (75%) did not develop tumor recurrence up to 24 weeks and displayed stronger IFN-γ-producing CTL responses against AFP, MAGE-1, and/or GPC-3 antigens than the others who developed recurrence after vaccination." (PMID 36139542, 2022). "For example, alpha-fetoprotein (AFP), Glypican-3 (GPC3), and folate receptor (FR) can be found on the tumor cell surface, but are rarely or not expressed in healthy cells." (PMID 35624643, 2022). "Add 11 variables: MVI, microscopic capsule, MRI tumor diameter, nonperipheral “washout”, HBP hypointensity, AFP, PIVKAII, GLOB, GGT, AFU, and CHOL." (PMID 35992871, 2022). "Based on the canonical marker gene expression, 3,085 cells were annotated as tumor cells (GPC3, EPCAM, AFP, ALB, DLK1), while 18,365 cells were designed as non-tumor cells." (PMID 35860547, 2022). "There is a lack of prognostic and predictive tumor markers for ICC, particularly compared with the clinical significance indicated by elevated AFP level and prognostic efficiency of PIVKA-II in HCC." (PMID 36330355, 2022). "The initial role of surgery in the treatment course is to obtain specimens for diagnosis, especially in cases presenting with negative tumor markers (i.e., human chorionic gonadotropin [HCG] and alpha-fetoprotein [AFP])." (PMID 36132131, 2022). "Only those lines that expressed both AFP and HLA-A*02 elicited release of IFN-γ and degranulation by AbTCR + co-stim T cells, indicating on-target/on-tumor activity, without evidence of off-target reactivity." (PMID 35840635, 2022). "Our study selected optimal features including four LI-RADS features (corona enhancement, enhancing capsule non-rim aterial phase hyperehancement, tumor size) and two non-LI-RADS features (internal arteries, non-smooth tumor margin) and AFP." (PMID 36439486, 2022). "AFP, a marker commonly used in HCC diagnosis, is positively correlated with the tumor size, but it remains negative in approximately 15–30% of HCC patients." (PMID 36100887, 2022). "VI) Due to incidental GBC, tumor markers (CEA, CA199, AFP, etc.)were not routinely tested in several patients." (PMID 36159808, 2022). "Lenvatinib was preferred for patients ≤ 60 years of age, AFP > 200 ng/mL, tumor size > 5 cm, without portal vein thrombosis, with previous anti-HCC treatment for TTP, and was preferred for patients ≤ 60 years of age and AFP > 200 ng/mL for PFS." (PMID 35337274, 2022). "Tumor markers including CEA, CA125, CA199, NSE, AFP were in normal range; No malignant cells were found by thin liquid-based cytology in bronchoscopy brush." (PMID 36595768, 2022). "The expression of FOXO6 in HCC tissues is significantly higher than that in normal and adjacent HCC tissues and is related to tumor size, TNM stage, AFP level, the presence or absence of HbsAg, and differentiation degree." (PMID 34123834, 2021). "The six variables significant for HCCDs in our study were sex, PET positivity, AFP and PIVKA-II values, largest tumor size regardless of viability, and NLR." (PMID 34203396, 2021). "Regarding biomarkers routinely available in daily practice, there are serum tumor markers like carcinoembryonic antigen (CEA), AFP, carbohydrate antigen (CA) 19-9 or CA15-3 that are not considered specific for diagnosis, but are used for treatment follow-up." (PMID 34943554, 2021). "Firstly, we screened and identified DEPs between AFP-negative HCC tissue and adjacent non-tumor liver tissue using SWATH-MS proteome technology, which included 14-3-3 zeta protein, a protein-binding protein." (PMID 34722278, 2021). "Baseline largest tumor size and number of tumors, TACE type/selectivity, AFP/MELD values, and ECOG did not have statistically significant effect on spleen volume." (PMID 34804911, 2021). "Blood and fecal routine, biochemistry testing, coagulation function, and tumor markers were negative, including human chorionic gonadotropin (HCG), alpha-fetoprotein (AFP), and carcinoembryonic antigen (CEA)." (PMID 33859949, 2021).
tumor (continued). "Tumor PD-L1 positivity was significantly correlated with age (P = 0.032), HBV positivity (P = 0.045), and high AFP level (P = 0.008) in the MTM type but not in the non-MTM type." (PMID 32770259, 2021). "In 6 patients, only serum levels of AFP and β-HCG were available, which were within the normal range, while in 7 patients, no preoperative tumor markers were available." (PMID 32504201, 2021). "The study found the antitumour effect of AFP occurs mainly through redirecting human T cells to specifically recognize and kill HCC tumor cells without significant toxicity to normal primary hepatocytes in vitro." (PMID 34696675, 2021). "In the LFP group, univariate analysis revealed that sex (male), HBs antigen-positive, HCV antibody negative, platelet count >11 × 104/μL, AFP > 400 ng/mL, DCP > 1600 AU/mL, tumor size >70 mm, and PVTT into trunk were poor prognostic factors." (PMID 34503259, 2021). "Baseline largest tumor size and number of tumors, TACE type/selectivity, AFP/MELD values, and ECOG did not have an effect on platelet count as these factors were dropped during model selection per AIC." (PMID 34804911, 2021). "AJCC stage, tumor size, grade, surgery and radiotherapy were predictors of OS and CSS in the non-chemotherapy group, while AJCC stage, tumor size, AFP, grade and surgery in the chemotherapy group." (PMID 34887446, 2021). "Crosstab analyses showed that exosomal S100A4 level was significantly correlated with serum alpha-fetoprotein (AFP) level, tumor size, vascular invasion, and TNM stage, but not with BCLC stage." (PMID 34035222, 2021). "According to the results of multivariate analysis, AFP > 400 ng/ml, ALR > 31, GPR > 0.48, MVI, absence of tumor capsule, and tumor size > 5 cm were independent prognostic factors for DFS." (PMID 34535132, 2021). "In correlation analysis, the common tumor makers CEA, AFP, CA125, CA153, CA199 showed no statistical correlation with immune cells." (PMID 34307453, 2021). "First, we screened and identified differentially expressed proteins between AFP-negative HCC tissue and adjacent non-tumor liver tissue using SWATH-MS proteome technology." (PMID 34722278, 2021). "Baseline total tumor size or largest tumor size and number of tumors, TACE type/selectivity, presence vascular invasion, and AFP/MELD values did not have statistically significant effect in the number of portosystemic collaterals." (PMID 34804911, 2021). "Whilst AFP has been commonly used as a serum biomarker of tumour response for HCC for many years, one of its major limitations is that approximately 30–50% of patients with HCC are AFP non-secretors." (PMID 34853657, 2021). "No clear elevation of tumor biomarkers including carcinoembryonic antigen (CEA), alpha fetoprotein (AFP), and carbohydrate antigen 125 (CA 125) was observed, while carbohydrate antigen 19-9 (CA 19-9) was a little higher (42.1 ng/ml)." (PMID 34527576, 2021). "On ROC analysis, AFP level and PIVKAII level showed no significance for well-moderate versus poor tumor grade (AUC=0.6, P= 0.2) and (AUC= 0.51, P= 0.8)." (PMID 34181327, 2021). "We also found that miR‐25‐3p expression was significantly correlated with tumour size, tumour number, tumour differentiation, vascular invasion and TNM stage (P < .05), but was not significantly correlated with gender, age or AFP level." (PMID 32525231, 2020). "Compared with AFP, GPC3 performs better in the early detection of HCC, and its capacity for diagnosis is not affected by the tumor size and stage." (PMID 32849835, 2020). "The characteristics of patients with small HCCs and those with non-HCC liver lesions differed in terms of age, AFP, ln(AFP), AST, ALT, PT (international normalized ratio), platelet count, and mean tumor size." (PMID 33193879, 2020).